PRPS1 (phosphoribosyl pyrophosphate synthetase 1)
Diseases named in the same sentence as PRPS1 in open-access papers (continued):
Sharing a sentence is not in itself a finding about the gene and the disease.
colorectal cancer (10 papers, 2016 to 2023). A primary or metastatic malignant neoplasm that affects the colon or rectum. "Human PRPS1 and PRPS2 gene products are implicated in drug resistance associated with recurrent acute lymphoblastic leukaemia and progression of colorectal cancer and hepatocellular carcinoma." (PMID 35741038, 2022). "The lncRNA lymphocytic leukemia 1 (DLEU1), targeting miR-320b/PRPS1, promotes the proliferation, migration, and invasion and reduces the apoptosis of colorectal cancer." (PMID 36203561, 2022). "In colorectal cancer cells, miR-124 directly targets phosphoribosyl pyrophosphate synthetase 1 (PRPS1) and ribose-5-phosphate isomerase-A (RPIA) and thus inhibits DNA synthesis and proliferation." (PMID 36013278, 2022). "PRPS1 is required for purine metabolism in glioma, colorectal cancer, and hepatocellular carcinoma formation." (PMID 33493137, 2021). "Human colorectal cancer cells had greater expression of PRPS1 than normal cells and defective PRPS1 enzymatic activity caused arrest of the cell cycle and delayed cell proliferation in the cancer cells." (PMID 34512699, 2021). "Ser103 phosphorylation of PRPS1 is suggested to be required for maintaining increased PRPS1 activity in colorectal cancer cells." (PMID 32650483, 2020). "Targeting PRPS1 by MicroRNA-124 reduces the proliferation of human colorectal cancer cells." (PMID 27425195, 2016). "It has been observed that PRPS1 is expressed constitutively, whereas PRPS2 is expressed inter alia in colorectal cancer (CRC) metastasis and hepatocellular carcinoma (HCC)." (PMID 35741038, 2022). "Furthermore, it has been shown that microRNAs can target the RPIA gene and the downstream PRPS1 gene that drives nucleoside formation from ribose-5-phosphate, leading to reduced PPP flux and proliferation in human colorectal cancer cells." (PMID 27328773, 2016).
deafness (10 papers, 2012 to 2025). An inherited or acquired condition characterized by the complete loss of the ability to hear from one or both ears. "Modest reductions in PRPS1 activity are associated with X-linked non-syndromic sensorineural deafness where patients have post-lingual progressive hearing loss (Deafness, X-linked 1 (DFNX1), MIM 304500)." (PMID 27425195, 2016). "In this study, we used NMN to investigate whether a reduction in NAD+ levels is a potential mechanism underlying PRPS1-related deafness." (PMID 40677922, 2025). "PRPS1 is considered the major determinant of PRPP levels, and the dysregulation of PRPS1 function is implicated in conditions such as deafness, optic neuropathy, gout, uric lithiasis, and childhood leukemia." (PMID 40295500, 2025). "Future research will focus on developing a PRPS1 variant (c.494G>A: p.Cys165Tyr) model in zebrafish and HEI-OC1 cells to comprehensively characterize the variant's role in deafness." (PMID 40677922, 2025). "Thus, our study explores the role of the deafness gene PRPS1 in HL, particularly through the NAD+/SIRT3/SOD2 pathway." (PMID 40677922, 2025). "This hypothesis is supported by our present data, especially by our transcriptome analysis as inherited deafness genes (such as COCH (coding for cochlin), TIMM8B, PRPS1 and tRNA synthetase) are downregulated in AK2-deficient cells." (PMID 26270350, 2015). "This variant has not been previously reported, and the mechanisms by which PRPS1 variants cause deafness remain unclear." (PMID 40677922, 2025).
gout (10 papers, 2015 to 2025). A condition characterized by painful swelling of the joints, which is caused by deposition of urate crystals. "PRPS-related gout/PRPS superactivity (OMIM phenotype number 300661) is an XLR condition due to an activating variant in PRPS1, resulting in hyperuricemia with sensorineural hearing loss, neurologic issues gout, and NL." (PMID 38606357, 2024). "For example, PRPS1 hyperactivity as a result of elevated PRPS1 transcription or gain-of-function mutations can lead to the classic X-linked disorder associated with hyperuricemia and hyperuricosuria, often causing gout in females and children." (PMID 35742917, 2022). "Because this gene mutation is more likely to occur in early-onset gout, thus, young patients with simple HUA should be screened for PRPS1 mutation." (PMID 35922835, 2022). "Gain-of-function PRPS1 variants result in PRPS superactivity (OMIM: 300661) with hyperuricemia and gout." (PMID 33294372, 2020). "So the purine overproduction gout (HGPRT deficiency, PRPS1 superactivity) was excluded in the family." (PMID 32090094, 2020). "For example, Hypoxanthine-Guanine Phosphoribosyltransferase (HPRT) deficiency and Phosphoribosyl Pyrophosphate Synthetase 1 (PRPS1) superactivity result in uric acid overproduction, which leads to gout." (PMID 30123371, 2018). "Studies have shown that HPRT and PRPS1 gene mutations seem to be the main cause of primary gout; SLC22A11 gene mutation is associated with RUE (renal underexcretion) gout; ABCG2 seems to be one of the reasons for the genetic heterogeneity of ROL (renal overload) and RUE gout." (PMID 35922835, 2022). "Furthermore, the detection of PRPS1 activity is great significance for the early diagnosis of HUA and gout." (PMID 35922835, 2022). "PRPS1 may be a potential target for the treatment of HUA and gout in the future." (PMID 35922835, 2022).
acute lymphoblastic leukemia (8 papers, 2018 to 2025). Leukemia with an acute onset, characterized by the presence of lymphoblasts in the bone marrow and the peripheral blood. "The PRPS1 mutation drove thiopurine resistance in childhood acute lymphoblastic leukemia." (PMID 36203561, 2022). "Relapse‐specific mutations in phosphoribosyl pyrophosphate synthetase 1 (PRPS1), a rate‐limiting purine biosynthesis enzyme, confer significant drug resistances to combination chemotherapy in acute lymphoblastic leukemia (ALL)." (PMID 30255549, 2018). "Mutations of PRPS1 could cause childhood drug resistance and relapse in acute lymphoblastic leukemia (ALL)." (PMID 33493137, 2021). "Moreover, PRPS1 plays an important role in the recurrence of relapsed acute lymphoblastic leukemia (ALL)." (PMID 31443513, 2019).
hyperuricemia (8 papers, 2014 to 2024). An abnormally high level of uric acid. "Hyperuricemia mediated by the loss of ADAR2 in the cortex correlates with the induction of phosphoribosyl pyrophosphate synthetase 1 (PRPS1), an essential enzyme involved in the synthesis of uric acid." (PMID 30619092, 2018).
breast carcinoma (7 papers, 2019 to 2025). "It has been reported that knockdown of PRPS1 expression suppresses proliferation and promotes apoptosis in neuroblastoma and human breast cancer cells." (PMID 40404919, 2025). "A number of X‐linked cancer‐related genes, including FLNA, PFC, PRPS1, TARD8, MAGEE1, TAF, and KLH4 have been associated with breast cancer." (PMID 38827026, 2024). "The X‐linked cancer‐related genes FLNA, PFC, PRPS1, TARD8, MAGEE1, TAF, and KLH4 have all been associated with breast cancer." (PMID 38827026, 2024). "KHK-A is involved in the phosphorylation and activation of phosphoribosyl pyrophosphate synthetase 1 and 14-3-3 eta protein, which promotes nucleic acid synthesis in hepatocellular carcinoma and triggers cell migration in breast cancer." (PMID 38971308, 2024). "In the fourth node, Phosphoribosyl pyrophosphate synthetase 1 (PRPS1) was found to be a direct target of miR124 in breast cancer." (PMID 30972106, 2019). "Moreover, silence of PRPS1 diminishes cell viability and promotes cell apoptosis in human breast cancer cells." (PMID 34113562, 2021). "Besides, silencing PRPS1 can increase cell apoptosis in human breast cancer cells and GBM." (PMID 31443513, 2019). "Furthermore, CP can have an epigenetic effect on cells, as shown in a breast cancer cell line that widely alters gene methylation, including inhibiting heat shock cognate B (HSCB) and phosphoribosyl pyrophosphate synthetase 1 (PRPS1) oncogene expression." (PMID 38785562, 2024).
hepatocellular carcinoma (7 papers, 2019 to 2024). A malignant tumor that arises from hepatocytes. "PRPS1 phosphorylation is also associated with poor prognosis in hepatocellular carcinoma, where it has been shown that fructokinase phosphorylates and activates PRPS1 to promote the pentose phosphate pathway and formate hepatocellular carcinoma." (PMID 31443513, 2019). "PRPS1 promotes pentose phosphate pathway-dependent de novo nucleic acid synthesis and hepatocellular carcinoma formation." (PMID 33493137, 2021). "KHK-A phosphorylates PRPS1 at Thr225 in the cytoplasm and activates it, which stimulates de novo nucleic acid synthesis through the pentose phosphate pathway; by so doing, it promotes hepatoma formation." (PMID 33116123, 2020). "Its substrates remained unknown and KHK-A has only recently been shown to act as protein kinase that directly phosphorylates phosphoribosyl pyrophosphate synthetase 1 (PRPS1) in the de novo nucleic acid synthesis pathway in human hepatocellular carcinoma cells." (PMID 32733884, 2020). "Hepatocellular carcinoma tumor cells switch the splicing of KHK-C to KHK-A, which activates phosphoribosyl pyrophosphate synthetase 1 to drive nucleic acid synthesis for tumor development." (PMID 38971308, 2024).
neuroblastoma (6 papers, 2019 to 2025). Neuroblastoma (NB) is the most common solid, extracranial childhood tumor. "Abnormally elevated level of PRPS1 is closely associated with poor prognosis in neuroblastoma, whereas suppression of PRPS1 alleviates cell proliferation and tumor growth." (PMID 34113562, 2021). "In contrast, patients that did not relapse had low PRPS1 expression levels, indicating that PRPS1 was closely associated with the recurrence of neuroblastoma." (PMID 31443513, 2019). "Moreover, circKIF2A has been implicated in neuroblastoma development by modulating PRPS1 expression through the suppression of miR-377-3p." (PMID 38282862, 2024). "Moreover, PRPS1 expression was associated with patient age, recurrence, and cause of death in neuroblastoma patients." (PMID 31443513, 2019). "Previous reports indicated that knockdown of PRPS1 strongly inhibited neuroblastoma cell proliferation." (PMID 36203561, 2022). "To address this knowledge gap, we investigated the effects of PRPS1 on the growth and proliferation of neuroblastoma cells in the present study." (PMID 31443513, 2019). "In this study, our data also revealed that mice implanted with PRPS1 knockdown neuroblastoma cells exhibited reduced tumor volume and weight." (PMID 31443513, 2019). "In this study, we found that PRPS1 was commonly expressed in neuroblastoma cells and was closely related to poor prognosis for cancer." (PMID 31443513, 2019). "Herein, we determined that PRPS1 expression was a potential prognostic marker in neuroblastoma patients." (PMID 31443513, 2019). "This suggests that we should further study changes in PRPS1 knockdown in neuroblastoma in the future." (PMID 31443513, 2019). "A report pointed out that c-MYC is a transcription factor of PRPS1 in neuroblastoma." (PMID 36203561, 2022). "Furthermore, the degree of tightness between cells was significantly lower in the experimental group than in the GFPsi group, indicating that PRPS1 was involved in the regulation of the tumorigenic ability of neuroblastoma." (PMID 31443513, 2019). "Thus, FCM was used to investigate the cell cycle of neuroblastoma cells in relation to PRPS1 expression." (PMID 31443513, 2019). "Neuroblastoma is a brain tumor; therefore, we speculate that PRPS1 works closely with MYCN to regulate cell proliferation in brain tumor neuroblastoma." (PMID 31443513, 2019). "Taken together, the results of our study demonstrate that PRPS1 is essential to the regulation of neuroblastoma cell proliferation and tumorigenesis, though the specific mechanism remains unclear." (PMID 31443513, 2019). "These analyses confirmed that PRPS1 was commonly expressed in neuroblastoma cells." (PMID 31443513, 2019). "In general, PRPS1 was closely related to poor neuroblastoma prognosis." (PMID 31443513, 2019). "Furthermore, down-regulation of PRPS1 inhibited neuroblastoma cell proliferation and tumor growth in vitro and in vivo via disturbing DNA synthesis." (PMID 31443513, 2019). "Developing therapeutics against PRPS1 could synergize with radiation and chemotherapy to achieve improved management of neuroblastoma." (PMID 31443513, 2019). "Overall, we boldly speculate that PRPS1 is closely related with MYCN to regulate cell proliferation in neuroblastoma." (PMID 31443513, 2019). "We found that PRPS1 was commonly expressed in neuroblastoma cells." (PMID 31443513, 2019). "A very close relationship was observed between PRPS1 expression and neuroblastoma prognosis." (PMID 31443513, 2019). "However, no investigation has been conducted to evaluate the role of PRPS1 in neuroblastoma and the molecular mechanisms underlying this relationship." (PMID 31443513, 2019). "However, the role of PRPS1 in neuroblastoma is still unclear." (PMID 31443513, 2019). "Also, the expression levels of PRPS1 were higher in patients that died of neuroblastoma." (PMID 31443513, 2019). "As we have shown, PRPS1 and PRPS2 have similar amino acid structures and may exhibit similar functions in neuroblastoma cells." (PMID 31443513, 2019).
neuropathy (6 papers, 2014 to 2022). A disorder affecting the nervous system that manifests with pain, tingling, numbness, and/or muscle weakness. "Neuropathy is a key feature of the human diseases associated with severe reduction of PRPS1 activity." (PMID 27425195, 2016). "Hearing loss could develop simultaneously with neuropathy, in some patients with pathogenic variants in PRPS1 (n = 1), NEFL (n = 2), MPZ (n = 1), TRPV4 (n = 1); or at a distance in some cases of variants in SH3TC2 (n = 2) and ABHD12 (n = 1)." (PMID 31393079, 2019). "The double mutant also showed abnormal development of primary motor neurons, hair cell innervation, and reduced leukocytes, consistent with the neuropathy and recurrent infection of the human patients possessing the most severe reductions of PRPS1 activity." (PMID 27425195, 2016).
Retinal dystrophy (5 papers, 2014 to 2023). Retinal dystrophy is an abnormality of the retina associated with a hereditary process. "This PRPS1 c.383A>T variant was previously reported at 70% mosaicism in a 17‐year‐old male with early onset retinal dystrophy, sensorineural hearing loss, axonal and demyelinating neuropathy on electromyogram, hypotonia, and developmental delay." (PMID 37927483, 2023). "Novel PRPS1 missense mutations were identified to cause retinal dystrophy in female patients, who were all heterozygous for the mutant alleles." (PMID 32650483, 2020). "One recent example is PRPS1, a gene in which heterozygous missense mutations were found to be carried by retinal dystrophy patients from 5 families in the 100,000 Genomes Project, providing robust genetic evidence for the cause of this condition." (PMID 30915099, 2019). "Very recently, Al-Maawali and colleagues expanded the PRPS1 phenotype to retinal dystrophy and diabetes insipidus in a family with two males affected with Leber’s congenital amaurosis along with other manifestations, and no carrier female affected." (PMID 25491489, 2014).
brain tumor (4 papers, 2019 to 2022). "PRPS1 was found to be active in brain tumour-initiating cells (BTICs), indicating that PRPS1 is vital for maintaining BTIC linking MYC with de novo purine synthesis." (PMID 35741038, 2022). "In brain tumor initiating cells, combined metabolomics and genomic analyses reveal specific upregulation of de novo purine synthesis through PRPS1." (PMID 33493137, 2021). "The knockdown of ADSL, GMPS, and PRPS1 decreases brain tumor initiating cell maintenance in both immunodeficient and immunocompetent mouse models." (PMID 32218208, 2020). "Previous evidence indicated that silencing MYC significantly reduced both mRNA and protein levels of PRPS1 in brain tumor-initiating cells, and chromatin immunoprecipitation assay showed that MYC interacted with the promoter regions of PRPS1 gene." (PMID 31443513, 2019).
glioma (4 papers, 2021 to 2023). A benign or malignant brain and spinal cord tumor that arises from glial cells (astrocytes, oligodendrocytes, ependymal cells). "Screening of a miRNA-targeting database identified PRPS1 mRNA as being negatively regulated by the expression of miR-154 in glioma CD133+ cells." (PMID 35741038, 2022). "Furthermore, the suppressed tumour formation of glioma CD133+ cells by reduction in PRPS1 expression is a result of increased cell apoptosis." (PMID 35741038, 2022). "PRPS1 plays a vital role in proliferation and apoptosis of glioma stem cells (GSCs)." (PMID 33493137, 2021). "Endoplasmic reticulum-induced stress via tunicamycin in glioma cells, together with the suppression of ERN1, downregulates PRPS1 and PRPS2 gene expression levels." (PMID 35741038, 2022). "The gene expression levels of H6PD, G6PD, ADSL, APRT, GMPS, PRPS1, and IMPDH1 in human glioma patients were significantly higher than those in the control group." (PMID 33723244, 2021). "Accordingly, the interaction between ERK5 and PRPS1/2 was confirmed via co-immunoprecipitation assays using either exogenous ERK5 and PRPS1/2 in cultured U-87MG cells, in vitro assay and endogenous ERK5 and PRPS1/2 in the glioma tissues." (PMID 36720864, 2023). "Furthermore, the expression of PRPS1, PRPS2, PRPSAP1 (PAP39) and PRPSAP2 (PAP41) genes in U87 glioma cells is not inhibited by ERN1 (EC 2.7.11, endoribonuclease activity of endoplasmic reticulum to nuclei-1)." (PMID 35741038, 2022).
X-linked deafness-1 (4 papers, 2012 to 2025). "Variants in the phosphoribosylpyrophosphate synthetase (PRPS1) gene have been shown to cause X-linked nonsyndromic hearing loss (HL) (DFNX1) in humans." (PMID 40494824, 2025).
Burkitt lymphoma (3 papers, 2020 to 2025). A rare form of malignant mature B-cell non-Hodgkin lymphoma. "To assess the requirement of Myc-driven, PRPS-dependent redox regulation in the context of fully transformed B cell lymphoma, we generated single-cell selected CRISPR/Cas9 knockouts of both PRPS1 and PRPS2 in CA46 and DG75 Burkitt’s lymphoma-derived cell lines." (PMID 39868212, 2025).
diabetes insipidus (3 papers, 2014 to 2018). A disorder characterized by excretion of large amounts of urine, accompanied by excessive thirst. "Recently, new mutations in PRPS1 have been identified that have been associated with novel phenotypes like diabetes insipidus expanding the spectrum of PRPS1-related diseases." (PMID 26089585, 2015). "For the first time, PRPS1 deficiency was associated with diabetes insipidus." (PMID 26089585, 2015).
glioblastoma (3 papers, 2017 to 2020). The most malignant astrocytic tumor (WHO grade IV). "Finally, PRPS1 is a direct target of miR-154 in CD133+ GBM cells in glioblastoma and can affect cellular proliferation and migration." (PMID 31443513, 2019). "Elevated expression of purine synthetic enzymes (PRPS1, ADSL, and GMPS) in metabolic subpathway 00230_5/00230_6 of the purine metabolic pathway is correlated with poor prognosis in glioblastoma patients." (PMID 33072547, 2020). "Besides, PRPS1 has important effects on cellular proliferation, clonality, and apoptosis in glioblastoma multiforme (GBM)." (PMID 31443513, 2019). "Importantly, shRNA knockdown of the purine synthesis enzymes PRPS1 (phosphoribosyl pyrophosphate synthetase 1), ADSL (adenylosuccinate synthase), or GMPS strongly suppressed the development of glioblastoma tumors in immunocompromised mice." (PMID 29257071, 2017).